C8orf48 (chromosome 8 open reading frame 48)
Synonyms: FLJ25402
Tractability: No criterion of Open Targets' tractability assessment is met for any kind of drug.
Gene: Protein-coding gene on chromosome 8 (13,566,869 to 13,568,288, forward strand). Ensembl gene ENSG00000164743.
Subcellular location (Human Protein Atlas): Cytosol; Nucleoplasm
Gene Ontology:
Molecular function: protein binding
Genetic constraint (gnomAD): Missense variants: 580 observed, 383.29 expected, observed/expected ratio (o/e) 1.51, 90% interval 1.41 to 1.62. Synonymous variants: 188 observed, 145.99 expected, observed/expected ratio (o/e) 1.29, 90% interval 1.14 to 1.45.
Homologues: Orthologues: chimpanzee C8H8orf48 (98% identical), pig C8orf48 (55% identical), rabbit C8orf48 (52% identical), mouse AI429214 (50% identical), rat C16h8orf48 (50% identical).
Diseases named in the same sentence as C8orf48 in open-access papers:
C8orf48 is named in the same sentence as 3 diseases in open-access papers, as found by Europe PMC text mining. Sharing a sentence is not in itself a finding about the gene and the disease. The quoted sentences say what the papers report.
breast carcinoma (1 paper, 2012). "A link between SGCZ, KIAA1456 or C8orf48 and breast cancer has not been established, however, DLC1 has been shown to inhibit cancer cell growth and been implicated as a tumor suppressor." (PMID 23056464, 2012).
cancer (2 papers, 2012 to 2023). A tumor composed of atypical neoplastic, often pleomorphic cells that invade other tissues. "In a much smaller number of publications, specific cancer-associated features of some ORF genes were studied, for example, the capability to form gene fusions, participation in the PPI subnetwork as hub genes and elucidation of upstream regulators (e.g., oncogene micro-RNA miR-556 for C8orf48 gene)." (PMID 37373333, 2023).
C8orf48 also shares sentences with these, for which no sentence is quoted: tumor (1 paper).